ST6GAL1 (ST6 beta-galactoside alpha-2,6-sialyltransferase 1)
Diseases named in the same sentence as ST6GAL1 in open-access papers (continued):
Sharing a sentence is not in itself a finding about the gene and the disease.
gastric cancer (10 papers, 2009 to 2025). A primary or metastatic malignant neoplasm involving the stomach. "In gastric cancer, ST6Gal1 elevated phosphorylation of AKT in association with the promotion of resistance against trastuzumab." (PMID 36106023, 2022). "Aberrant sialylation is causally linked to therapy resistance in cancer, and ST6GAL1 has been identified as a mediator of treatment resistance in several tumour types, including pancreatic cancer, colorectal cancer, leukaemia, and gastric cancer." (PMID 39272811, 2024). "For example, ST6GAL1 is upregulated in pancreatic, colon, ovarian, and gastric cancers, and high ST6GAL1 expression correlates with a poor prognosis." (PMID 39615678, 2024). "In organoids derived from gastric cancer, ST6Gal1 expression depended upon stem cell maintenance factors with an important role for Wnt." (PMID 36106023, 2022). "Similarly, the sex-determining region Y-box protein 5–Twist family BHLH transcription factor 1 pathway, a master regulator of EMT in prostate and gastric cancers, was significantly upregulated in ST6GAL1-overexpressing SW48 cells." (PMID 39937175, 2025). "Furthermore, upregulation of ST6GAL1 was shown to enhance resistance to TNF-mediated apoptosis in gastric cancer-derived organoids, suggesting a role for ST6GAL1 in epithelial cell longevity of gastric adenocarcinoma." (PMID 33921986, 2021).
cervical cancer (9 papers, 2010 to 2025). A primary or metastatic malignant neoplasm involving the cervix. "A previous study also found that high expression of ST6GAL1 is associated with poor outcomes in melanoma, hepatocellular, breast, and cervical cancers." (PMID 33836687, 2021). "Importantly, 466 of 658 mRNAs were significantly associated with ST6GAL1 expression in TCGA cervical cancer dataset." (PMID 34745942, 2021). "Taken together, we thus speculated that ST6GAL1 may have an important role in cervical cancer, especially in high-risk HPV-induced carcinogenesis." (PMID 34745942, 2021). "Moreover, it was found that high expression of ST6GAL1 was associated with more invasive properties of cervical cancer and that the reduced expression of ST3GAL1, ST3GAL3, and ST3GAL4 may also contribute to the characteristics of cervical cancer." (PMID 30375371, 2018). "Taken together, these results demonstrate that ST6GAL1 depends on activating cGMP/PKG signaling axis to play oncogenic activities in C33A cervical cancer cells." (PMID 34745942, 2021). "In-depth analyses further revealed that α2,6-sialyltransferase, ST6GAL1, was a novel E6-induced oncogenic protein and performed oncogenic activities in both E6-positive and E6-negative cervical cancer cells." (PMID 34745942, 2021). "Taken together, these data demonstrate a crucial oncogenic role of ST6GAL1 in both E6-positive and E6-negative cervical cancer cells." (PMID 34745942, 2021). "α-2,6 sialic acids and the corresponding glycosyltransferase ST6GAL1 were significantly increased in E6 stable-expressing HPV− cervical cancer C33A cells." (PMID 34745942, 2021). "Knockdown of ST6GAL1 suppresses subcutaneous tumor growth and increases cisplatin sensitivity of cervical cancer cells; we therefore presumed that ST6GAL1 may be a candidate oncogenic mediator of HPV16 E6 protein." (PMID 34745942, 2021). "Moreover, we found that blocking cGMP/PKG signaling with ODQ eliminates the oncogenic activities of both E6 and ST6GAL1 in cervical cancer cells." (PMID 34745942, 2021). "Thus, E6 may play a sophisticated role in the progression of cervical cancer, and the detailed molecular targets of ST6GAL1 need to be further identified for unveiling its contribution in E6-induced carcinogenesis." (PMID 34745942, 2021). "Therefore, ST6GAL1 or cGMP/PKG signaling might be novel targets for the development of drugs against cervical cancer." (PMID 34745942, 2021). "Therefore, our findings provide novel insights into the molecular mechanisms involved in HPV16 E6-induced oncogenesis and suggest that targeting ST6GAL1 or cGMP–PKG signaling might be potential therapeutic strategies for cervical cancer." (PMID 34745942, 2021). "Furthermore, ST6GAL1 positively associates with E6 expression in cervical samples and serves as an important oncogenic mediator in both HPV16 E6-positive and E6-negative C33A cervical cancer cells." (PMID 34745942, 2021). "Knockdown of O-GlcNAc transferase (OGT) or ST6GAL1 suppresses tumorigenesis and metastasis of HPV18+ cervical cancer Hela cells." (PMID 34745942, 2021). "In the present study, we confirmed that E6 increases level of α2-6 sialic acids in cervical cancer HPV− C33A cells via using Lectin microarray, and ST6GAL1 is an important mediator for E6 to perform oncogenic activities." (PMID 34745942, 2021). "Taken together, these data demonstrate a requirement for ST6GAL1-cGMP/PKG signaling axis in oncogenic properties of E6 and supports its inhibition as a viable therapeutic strategy against cervical cancer." (PMID 34745942, 2021). "Most importantly, knockdown ST6GAL1 or target inhibition of cGMP/PKG pathway suppressed colony formulation and metastasis of cervical cancer cells." (PMID 34745942, 2021). "Importantly, knockdown ST6GAL1 or blocking cGMP/PKG pathway with specific inhibitor ODQ suppressed the oncogenic activities of both E6-positive and E6-negative cervical cancer cells." (PMID 34745942, 2021).
cervical cancer (continued). "ST6GAL1, responsible for the terminal α2,6-sialylation of N-glycans, can be upregulated by HPV16 E5 oncoprotein, and its inhibition increases cisplatin sensitivity of HPV18+ cervical cancer cells." (PMID 34745942, 2021). "E6/ST6GAL1 triggered the activation of downstream cGMP/PKG signaling pathway and ODQ (inhibitor of GMP production) simultaneously suppressed the oncogenic activities of both E6 and ST6GAL1 in cervical cancer cells." (PMID 34745942, 2021). "Taken together, these findings indicate that ST6GAL1 is an important mediator for oncogenic E6 protein to activate the downstream cGMP/PKG signaling pathway, which represents a novel molecular mechanism and potential therapeutic targets for cervical cancer." (PMID 34745942, 2021).
bladder cancer (8 papers, 2014 to 2024). "Given the observation of ST6GAL1 expression loss in the course of bladder cancer progression, we attempted to decipher the molecular cause for ST6GAL1 gene silencing." (PMID 25465919, 2014). "It appears that loss of ST6GAL1 expression in bladder cancer is not only a common event, but also tightly associated with epigenetic changes within the ST6GAL1 promoter region." (PMID 25465919, 2014). "Thereafter, using patient matched samples, a sequential loss of ST6GAL1 could be demonstrated throughout the course of bladder cancer development beginning in the CIS stage and continuing to invasive disease when compared with the corresponding normal urothelium." (PMID 25465919, 2014). "The P3 promoter for the ST6GAL1 YZ isoform has a prominent CpG island that is reportedly hypermethylated in certain types of cancer, including glioblastoma and bladder cancer." (PMID 39260693, 2024). "Among the 412 bladder cancer samples, 42 (10.19%) experienced mutation in the 8 SiaTs which were ST6GALNAC1, ST3GAL6, ST8SIA2, ST6GAL2, ST6GAL1, ST6GALNAC5, ST6GALNAC3, and ST3GAL5." (PMID 37968767, 2023). "The downregulation of ST6GAL1 decreased metalloproteinases (MMPs) expression and suppressed invasive potential of A549 and H1299 cells in vitro, whereas bladder cancer has ST6GAL1 upregulation, a tumor-suppressive role." (PMID 34943806, 2021). "Further investigation is warranted in order to more precisely assess the mechanism by which ST6GAL1 contributes to bladder cancer formation, progression and invasion." (PMID 25465919, 2014). "In light of differential ST6GAL1 mRNA expression in bladder cancer, we performed immunohistochemical ST6GAL1 protein expression in NU as well as in bladder tumor tissues." (PMID 25465919, 2014). "Based on the TCGA data we verified downregulation of ST6GAL1 gene expression in bladder cancer in comparison to normal bladder tissues." (PMID 25465919, 2014). "Based on the promoter methylation in bladder cancer cell lines, the ST6GAL1 promoter methylation in primary human bladder cancer samples including CIS (n = 82) was analyzed using MSP technology." (PMID 25465919, 2014). "Our study characterizes for the first time ST6GAL1 expression and regulation during bladder cancer development." (PMID 25465919, 2014). "However, more recent studies examining ST6GAL1 protein expression have indicated that ST6GAL1 is upregulated in glioblastoma and bladder cancer, consistent with the overexpression of ST6GAL1 in most other cancer types." (PMID 39260693, 2024). "As such, we sought to determine whether promoter methylation could be responsible for ST6GAL1 gene inactivation in bladder cancer as well." (PMID 25465919, 2014). "Therefore, the current study seeks to further elucidate ST6GAL1 expression and its regulation in order to determine the potential impact of the glycosyltransferase ST6GAL1 on bladder cancer development." (PMID 25465919, 2014). "Finally, demethylating treatment of methylated ST6GAL1 bladder cancer cell lines with 5-aza-2-deoxycytidine clearly restored ST6GAL1 expression, thus functionally confirming a strong correlation between ST6GAL1 expression and its promoter hypermethylation." (PMID 25465919, 2014). "Importantly, we significantly revealed an inverse correlation between ST6GAL1 mRNA expression and ST6GAL1 promoter merthylation in primary bladder cancer." (PMID 25465919, 2014). "Of clinical importance, in our comprehensive sample collection, ST6GAL1 expression loss correlated with clinico-pathological metastasis, i.e. regional lymph node invasion, implying a possible tumor suppressive role for ST6GAL1 in advanced bladder cancer stages." (PMID 25465919, 2014). "Our findings give the first indications that this major epigenetic mechanism could be important in the regulation of ST6GAL1 expression in bladder cancer as well." (PMID 25465919, 2014). "This is the first study to describe ST6GAL1 expression and regulation in human bladder cancer." (PMID 25465919, 2014).
bladder cancer (continued). "Therefore we aimed to study for the first time ST6GAL1 expression and regulation in bladder cancer." (PMID 25465919, 2014). "Therefore, we assessed whether this epigenetic modification might be responsible for ST6GAL1 downregulation in bladder cancer as well." (PMID 25465919, 2014). "However, the impact of ST6GAL1 in bladder cancer remains unclear to date." (PMID 25465919, 2014). "MSP analysis showed indeed distinct DNA methylation in the human bladder cancer cell line J82 and RT112 at the ST6GAL1 promoter region." (PMID 25465919, 2014). "On the contrary, ST6GAL1 downregulation was observed in bladder cancer, but the expression of ST6GAL1 has not yet been analyzed in different types of thyroid cancer." (PMID 38003522, 2023). "Semi-quantitative ST6GAL1 real-time PCR expression analysis was performed on 51 bladder cancer tissue samples including flat (n = 12 CIS), papillary non-invasive (n = 13 pTa), and muscle-invasive (n=26 pT2-4) bladder tumor samples." (PMID 25465919, 2014). "Up to date, knowledge about a possible role of ST6GAL1 in human bladder cancer is still lacking." (PMID 25465919, 2014).
glioma (8 papers, 2015 to 2025). A benign or malignant brain and spinal cord tumor that arises from glial cells (astrocytes, oligodendrocytes, ependymal cells). "Notably, transfection of the same cells with α2,6-sialyltransferase I (ST6GAL1), which catalyzes the addition of α2,6-linked sialic acids, suppressed glioma cell invasion." (PMID 39728102, 2024). "Through database analyses, it found that ST6GAL1 expression is elevated in glioma tissues and cells." (PMID 33836687, 2021). "Substantial reports have shown that ST6GAL1 is overexpressed in various types of cancer, such as oral, ovarian, prostate, hepatic, and glioma." (PMID 33836687, 2021). "In gliomas, ST6GAL1 promotes GBM growth through α2,6-sialylation." (PMID 41445790, 2025). "In addition, glioma cells expressing ST6GAL1 did not initiate tumors in vivo, suggesting that the abundance of terminal α2,6-linked sialic acids is a negative regulator of glioma cell invasion." (PMID 39728102, 2024). "While these pathways are known to play critical roles in brain tumors, the levels, or ability, of ST6GAL1, ST6GAL2, or α2,6 sialylation to modulate BTIC signaling or maintenance to increase glioma growth has not been investigated." (PMID 36345944, 2022).
viral infection (8 papers, 2009 to 2025). "Although sialic acid presentation is important in EV-D68 infections, a previous gene trap showed that ST6GAL1, which mainly catalyzes 2,6-linked sialic acid formation, is considerably more important than ST3GAL4 in HAP-1 cells for viral infection." (PMID 28446605, 2017). "The genome copy number of viruses was reduced following transfection of the various cell lines (A549, HBE, and HEp-2) with ST6GAL1 siRNAs prior to viral infection." (PMID 24670114, 2014). "Furthermore, genetic depletion of several other factors, such as ASGR1, ASGR2, and ST6GAL1, also impaired viral infection, albeit with a 10–20% reduction." (PMID 39173055, 2024). "We first determined the dependency of virus infection efficiency on the density and specificity of Sia receptors on the surface of HEKΔSia cells that were co-transfected with a concentration range of sialyltransferases ST6Gal1 or ST3Gal4." (PMID 35831293, 2022). "This recombinant ST6Gal1 obtained using a silkworm expression system is a valuable tool for investigating the molecular mechanisms of biological and physiological events, such as cell-cell recognition and viral infections." (PMID 19500344, 2009). "Results from the screen and subsequent analysis highlighted that several genes involved in sialic acid synthesis, including ST3GAL4, ST6GAL1, and SLC35A1, are important for viral infection." (PMID 40767522, 2025). "In contrast, CPE (%) was dramatically reduced in ST6GAL1 siRNA-transduced 16-HBE cells, indicating the ST6GAL1 siRNA-treated cells were protected from the PR8 virus infection." (PMID 35044216, 2022). "However, we could only identify ST3GAL4, not ST6GAL1, as an essential factor for viral infection in HeLa cells." (PMID 28446605, 2017).
diabetes (7 papers, 2015 to 2025). "Using UK Biobank data, we sought to confirm an association between ST6GAL1 and T2D (17 384 cases, 317 887 controls) and analysed rs6783836 against markers of diabetes, inflammation and psoriasis." (PMID 35467766, 2022). "The N-glycosylation site of ST6GAL1 has a profound implication on diabetes susceptibility." (PMID 39130628, 2024). "Diabetics are at an increased risk of developing HFS and we confirmed an association for ST6GAL1 with T2D, and also found that rs6783836 was associated with glycated haemoglobin levels, a marker routinely used in the diagnosis and monitoring of diabetes, supporting an interrelationship." (PMID 35467766, 2022). "Both psoriasis and diabetes are associated with the PTPN22, ST6GAL1, and JAZF1 genes." (PMID 40660159, 2025). "The link between psoriasis and diabetes could, in part, be explained by the rise in obesity and unhealthy lifestyles, the insulin resistance associated with inflammation, and the presence of various genes (CDKAL1, PTPN22, ST6GAL1, JAZF1) linked to both conditions." (PMID 38541672, 2024). "In the type II enzyme family of α-2, 6 sialyltransferases, ST6gal1, St6galnac2, and 3 are highly expressed in kidney IM but they did not change in diabetes." (PMID 26483702, 2015).
influenza (7 papers, 2010 to 2024). An acute viral infection of the respiratory tract, occurring in isolated cases, in epidemics, or in pandemics; it is caused by serologically different strains of viruses (influenzaviruses) designated A, B, and C, has a 3-day incubation period, and usually lasts for 3 to 10 days. "Genome-wide analyses identify variants in B3GALT5 and ST6GAL1 associated with influenza susceptibility." (PMID 39103650, 2024). "In a multiancestry meta-analysis of medical record influenza, we observed directionally consistent and genome-wide significant associations with both rs16861415 in ST6GAL1 (OR = 0.90, P = 3.0 × 10−10) and rs2837112 in B3GALT5 (OR = 0.93, P = 2.5 × 10−11)." (PMID 39103650, 2024). "Meanwhile, the increase in DPP4 (MERS-CoV), ST3GAL4, and ST6GAL1 (influenza) was associated with increased goblet and basal activated cells." (PMID 34198852, 2021). "A possible explanation for this is that there was greater efficiency of infection as a result of a deficient systemic influenza-specific humoral response in these ST6GAL1 knock-out mice." (PMID 24670114, 2014). "For these experiments, we focused on two likely effector genes of influenza-associated variants—ST6GAL1 and B3GALT5—because of their potential role in a critical step of influenza virus infectivity, that is, modulation of α-2,6-linked sialic acid abundance at the cell surface." (PMID 39103650, 2024). "Of the four likely effector genes of the influenza loci, ST6GAL1 and B3GALT5 are strong biological candidates (ADIPOQ and IGSF5 are discussed in the Supplementary Note)." (PMID 39103650, 2024). "We identified and replicated the first genome-wide-significant loci for influenza and demonstrated that inhibition of ST6GAL1 reduces viral infectivity in vitro." (PMID 39103650, 2024). "Knockdown of ST6GAL1 in cell culture reduces influenza infectivity, likely by interfering with the glycoprotein modifications required for viral entry." (PMID 39103650, 2024). "In vitro small interfering RNA knockdown of ST6GAL1—an enzyme that adds sialic acid to the cell surface, which is used for viral entry—reduced influenza infectivity by 57%." (PMID 39103650, 2024). "Interestingly, ST6GAL1 seems to be an important enzyme during influenza infection, since the virus uses sialic acid-containing glycans as cellular entry points." (PMID 35784319, 2022). "The siRNAs targeting ST6GAL1 that we used in this current study could be ideal in preventing influenza infection in patient groups with low immunity." (PMID 24670114, 2014). "siRNAs against ST6GAL1 achieved approximately 90% expression knockdown and resulted in approximately 80% reduction in sialic acid abundance at the cell surface and approximately 50% reduction in influenza infectivity, which is consistent with previous findings." (PMID 39103650, 2024). "Therefore, ST6GAL1 could be a potential target for anti-influenza therapeutics." (PMID 24670114, 2014). "In particular, the generation of influenza-specific humoral responses is impaired in mice lacking ST6GAL1, while ST3GAL1 regulates apoptosis of CD8+ T cells." (PMID 20174570, 2010). "Furthermore, we discovered and replicated an association between influenza infection and noncoding variants in B3GALT5 and ST6GAL1, neither of which was associated with COVID-19." (PMID 39103650, 2024).